NLRP3 (NLR family pyrin domain containing 3)
Diseases named in the same sentence as NLRP3 in open-access papers (continued):
Sharing a sentence is not in itself a finding about the gene and the disease.
memory impairment (30 papers, 2017 to 2026). "NLRP3 inflammasomes have been proven by a previous study to be activated by ROS generation, which cause D-gal-triggered learning and memory impairment in mice." (PMID 38397781, 2024). "In contrast, the mice with NLRP3 expression exhibited spatial memory impairment, reduced spine density, increased locomotion, and slowed habituation." (PMID 40427569, 2025). "Microglial NLRP3 activation, system-level interactions, and memory impairment have emerged as key research hotspots in AD." (PMID 41445867, 2025). "Our findings suggest that TNEA attenuates AD-associated memory impairment via promoting TFEB/TFE3-mediated autophagic clearance of Aβ and NLRP3 inflammasome, and partially reveal the molecular basis of combined acupoints therapy originated from ancient wisdom." (PMID 36732771, 2023). "Collectively, these findings revealed that NLRP3-mediated pyroptosis played a detrimental role in the etiology of LPS-induced memory impairment, and DNLA acted as a promising therapeutic agent for the prevention and treatment of AD." (PMID 35586062, 2022). "It showed that treatment with mefenamic acid was protective against Aβ-induced memory impairment and NLRP3-mediated neuroinflammation in AD animal models." (PMID 36160384, 2022). "The hippocampus-dependent memory impairment induced by the cecal perforation (CLP) was accompanied by increased levels of NLRP3, caspase-1, and proinflammatory cytokines." (PMID 35571246, 2022). "We found that AST-120 treatment significantly reduced both the serum and brain levels of IS, ameliorated NLRP3 inflammasome-induced neuroinflammation in the hippocampus, and improved short-term and long-term memory impairment in CKD mice." (PMID 34572437, 2021). "Similarly, some scholars revealed that exhaust particulate activated hippocampal microglial cells, which induced NLRP3 inflammasome activation, consequently leading to learning and memory impairment." (PMID 38570868, 2024). "Furthermore, the expression of NLRP3 inflammasome is elevated in the memory impairment, which was significantly attenuated by administration of S2 extract." (PMID 36771724, 2023). "In the present study, we confirmed that SH could ameliorate Aβ1-42-induced memory impairment, neuroinflammation, and pyroptosis through inhibiting the NLRP3/GSDMD pathway in AD." (PMID 34188608, 2021). "In summary, we demonstrated that SH could ameliorate Aβ1-42-induced memory impairment, neuroinflammation, and pyroptosis through inhibiting the NLRP3/GSDMD pathway in AD." (PMID 34188608, 2021). "Therefore, HMGB1 may be an important reason for NLRP3 inflammasome-induced memory impairment in the late stage of TBI." (PMID 34666797, 2021). "In summary, our study demonstrates that microglial NLRP3 inflammasome activation in a NOX2-dependent manner contributes to As(III)-induced neurodevelopmental deficits, particularly in learning and memory impairments." (PMID 40710983, 2025). "In AD, sodium houttuyfonate (SH), one of the major extracts from houttuynia cordata, has been shown to inhibit NLRP3/GSDMD, a pathway responsible for memory impairment, inflammation, and pyroptosis." (PMID 36713841, 2023). "The inhibition of NLRP3 inflammasome by MCC950 improved synaptic plasticity deficits in vivo, and ameliorated memory impairment in murine models." (PMID 36160384, 2022). "Strawberry and selenium, when administered individually, significantly attenuated memory impairment, oxidative stress, neuroinflammation, and apoptosis, as evidenced by marked normalization of Nrf2/HO-1, TAC, SOD, MDA, TLR4/NF-κB/TNF-α, NLRP3/CASP-1/IL-1β, and BAX/Bcl-2 signaling." (PMID 41471381, 2025). "MH administration exerted neuroprotective effect against memory impairment and improved locomotor activity in rodents via inhibition of oxidative stress markers/release of proinflammatory cytokines and suppression of protein expression of NF-kB/TLR4/NLRP3." (PMID 36015160, 2022).
amyloid (29 papers, 2011 to 2026). "The NLR family pyrin domain containing 3 (NLRP3) inflammasome, part of the innate immune system, has been implicated in the neuropathology of both preclinical amyloid and tau transgenic models." (PMID 39381137, 2024). "Conversely, it has been shown that an NLRP3 deficiency can suppress brain caspase-1 and IL-1β activation, which remarkably inhibits amyloidosis and neuropathology, and ultimately enhances cognitive function in the AD mice model." (PMID 35327507, 2022). "Previous reports showed that early treatment with IL-1 inhibitors Anakinra or Canakinumab in patients with NLRP3 mutations can improve hearing and prevent irreversible renal damage from amyloidosis." (PMID 27965898, 2016). "Our data further suggest that pharmacological inhibition of NLRP3, after disease onset, has the potential to reduce cortical and hippocampal amyloid burden." (PMID 40343261, 2025). "Together, these findings further represent a core therapeutic relevance of NLRP3 inhibition and a contextual mechanistic link between CASM-deficiency and amyloid pathology." (PMID 40343261, 2025). "What's more, this nano-theranostic platform based on SDP@Cur-CRT/QSH also reduce the amyloid plaque burden via NLRP3 inflammasome inhibition in neurons and microglia." (PMID 35836190, 2022). "The overexpression of Klotho has been reported to suppress neuroinflammation by inhibiting the NLRP3/caspase-1 pathway in amyloidosis mouse models." (PMID 35327507, 2022). "First, NLRP3 contributes to amyloid pathology by regulating the phagocytic capacity of microglia in AD." (PMID 33847763, 2021). "Together, these results suggest that a LPS elicited peripheral immune challenge affects amyloid deposition in aged APP/PS1 mice in an NLRP3‐dependent manner." (PMID 31359456, 2019). "Furthermore, inhibition of Aβ‐induced activation of the NLRP3 inflammasome was found to result in reductions in amyloid plaque in vivo, suggesting a positive feedback relationship between microglial inflammasome activation and Aβ pathology." (PMID 35474599, 2022). "Moreover, the same study showed that even at a later point of amyloidosis progression, inhibition of the NLRP3 inflammasome can efficiently reduce the effects of amyloid accumulation and oxidative stress." (PMID 36012243, 2022). "It has been demonstrated that depletion of NLRP3 could significantly suppress amyloidosis and neuropathology, as well as improve cognitive function in AD mice, indicating that the NLRP3 inflammasome is a possible molecular target for neuroprotection and therapeutic intervention in AD." (PMID 28473983, 2017). "The study highlights the pivotal role of the NLRP3-ASC inflammasome—comprising the NACHT, LRR, and PYD domains-containing protein 3 (NLRP3) and ASC (CARD-containing apoptotic speck-like protein)—in amyloid-β-induced microgliopathy and amyloid pathology." (PMID 40538660, 2025). "In support of this previous hypothesis, inhibition of NLRP3 by a specific inhibitor, MCC950, improved amyloid plaque pathology and cognitive function in AD mouse models." (PMID 36142143, 2022). "Moreover, global inflammasome inactivation through respectively full body deletion of caspases 1 and 11 in AppNL-G-F mice and Nlrp3 deletion in APP/PS1 mice also failed to modulate amyloid pathology and disease progression." (PMID 38352874, 2024). "Importantly, the NLRP3–ASC inflammasome pathway thereby presents as a highly interesting target, concomitantly positively modulating three key pathogenetic features of AD, i.e., Tau pathology, amyloid pathology and neuroinflammation." (PMID 30721409, 2019). "NLRP3 selective inhibitors (e.g. MCC950, OLT1177) that have shown effective for reversing AD pathology in amyloid mouse models, might not be enough to suppress IL-1β levels and the detrimental effects of IL-1β in human AD." (PMID 38539253, 2024).
pulmonary hypertension (29 papers, 2015 to 2025). Increased pressure within the pulmonary circulation due to lung or heart disorder. "Recently, the selective P2X7 receptor antagonist A-740003 was reported to significantly attenuate the NLRP3 inflammasome upregulation and decrease the mean right ventricular (RV) pressure and RV hypertrophy associated with pulmonary hypertension." (PMID 33494430, 2021). "Furthermore, the ASC adaptor protein of the NLRP3 inflammasome, was shown to be critical in hypoxia-induced pulmonary hypertension and right ventricular remodeling which was associated with increased protein levels of caspase-1, IL-18, and IL-1β." (PMID 32093005, 2020). "A number of studies have demonstrated the association of NLRP3 inflammasome and GSDMD in pulmonary hypertension." (PMID 40948742, 2025). "Meanwhile, macrophage NLRP3 activates CCR2+ monocyte-derived macrophages, increases NLRP3 expression, and contributes to pulmonary hypertension-induced ventricular failure." (PMID 39935606, 2025). "Our ongoing research has also indicated the relation of DAMP molecules and NLRP3 inflammasome in inducing pulmonary hypertension, which is consistent with other studies." (PMID 40948742, 2025). "This review summarizes the regulatory roles of S100 protein family in NLRP3 inflammasome signaling and their functions in innate and adaptive immunity, with an emphasis on pulmonary hypertension." (PMID 40948742, 2025). "Numerous studies have demonstrated that Sil can significantly lower IL-18 levels of burned rat model heart tissue and that Sil treatment can lower NLRP3 expression in the lungs of animals with pulmonary hypertension." (PMID 37636019, 2023). "It has been proposed that pulmonary arterial endothelial cell ferroptosis mediates the progression of pulmonary hypertension through the MCT-induced HMGB1/TLR4/NLRP3 inflammasome signaling pathway in rats." (PMID 38111578, 2023). "Recent data from animal studies suggest a role for the NLRP3 inflammasome in the progression of pulmonary hypertension (PH), but its exact contribution is still poorly defined." (PMID 35833096, 2022). "Pre-clinical and clinical studies further support the involvement of the NLRP3 inflammasome in pulmonary hypertension and confirm the occurrence of pyroptosis in rat pulmonary arteries and hypoxic human pulmonary smooth muscle cells." (PMID 33494430, 2021). "Our study shows that NLRP‐3 is involved in regulating the expression of IL‐8 and IL‐1β in rats with pulmonary hypertension." (PMID 33295020, 2021). "The results of immunofluorescence and immunohistochemistry showed that AS‐IV inhibited the expression of calpain‐1 and NLRP‐3 in pulmonary tissue of rats with pulmonary hypertension, and the inhibitory effect was similar to that of MCC950 and MDL‐28170." (PMID 33295020, 2021). "The phenolic compound ellagic acid ameliorates monocrotaline-induced pulmonary artery hypertension in rats via inhibiting the NLRP3 inflammasome signaling pathway, mostly due to its anti-oxidative properties." (PMID 33494430, 2021). "Recent evidence shows that NLRP3 is involved in pulmonary vasoconstriction and progressive pulmonary hypertension." (PMID 31915037, 2020). "Similar results exhibited that EA prevented monocrotaline-induced rat pulmonary artery hypertension via inhibiting the activation of the NLRP3 inflammasome and caspase-1 in the lungs and release of proinflammatory cytokines, such as IL-β, in serum." (PMID 33294118, 2020). "Arctigenin ameliorates monocrotaline-induced pulmonary arterial hypertension, at least in part, through exerting its anti-inflammatory, antioxidant, and antiproliferative effects, which inhibit the NLRP3 inflammasome signal pathway in rats." (PMID 35521617, 2018). "An anti-oxidant has been shown to ameliorate experimental pulmonary artery hypertension via inhibiting NLRP3 inflammasome signal pathway in rats." (PMID 26523150, 2015).
pulmonary hypertension (continued). "Therefore, we suggest that the inflammatory response mediated by NLRP‐3/calpain‐1 is involved in the development of pulmonary hypertension." (PMID 33295020, 2021). "For the first time, we observed the improvement of the inflammatory response mediated by NLRP‐3/calpain‐1 as a breakthrough that could scientifically explain the prevention and treatment effects of AS‐IV on pulmonary hypertension." (PMID 33295020, 2021). "Although more research is clearly needed to better define the exact mechanisms mediated by the NLRP3 inflammasome in leading to pulmonary hypertension, the current evidence surely hints to this pathway as a presumed therapeutic target in this devastating disease." (PMID 33494430, 2021). "In conclusion, in this study the results suggested that AS‐IV could inhibit monocrotaline‐induced pulmonary arterial hypertension via the NLRP‐3/calpain‐1 pathway." (PMID 33295020, 2021). "In addition to targeting NLRP3, in a model of pulmonary arterial hypertension (PAH), miR-223 can suppress the expression of the Integrin-β 3 subunit gene (ITGB3) to alleviate the progression of PAH and avoid the dysfunction of pulmonary arterial endothelial cells." (PMID 37465640, 2023). "However, the mechanism underlying the protective effect of AS‐IV on MCT‐induced pulmonary hypertension in rats mediated by the NLRP‐3/calpain‐1 signalling pathway is not clear." (PMID 33295020, 2021). "Both NLRP3 and GSDMD have been found playing a role in pulmonary hypertension by activating the proinflammatory cytokines and releasing cytosolic contents into the extracellular space." (PMID 40948742, 2025). "Understanding the interactive and feedback mechanism between NLRP3 inflammasome, S100A8/A9, and GSDMD is necessary to explore their role in pulmonary hypertension." (PMID 40948742, 2025). "In other studies using MCT to establish a rat model of pulmonary hypertension (PH), peroxiredoxin 6 (PRDX6) was found to regulate ferroptosis in PAECs through HMGB1 release and activation of the TLR4/NLRP3 inflammasome signaling pathway." (PMID 38111578, 2023). "We used the NLRP‐3 inflammasome inhibitor (MCC950) and the calpain‐1 inhibitor (MDL‐28170) to verify that AS‐IV protected rats against pulmonary hypertension induced by MCT through the NLRP‐3/calpain‐1 signalling pathway." (PMID 33295020, 2021). "In animal models of pulmonary hypertension induced by monocrotaline (MCT), the activation of P2X7 receptors is accompanied by an increase in NLRP3 inflammasome and IL-1β." (PMID 33995071, 2021). "However, the contribution of NLRP3 inflammasome, S100A8/A9, and GSDMD as a team to pulmonary hypertension is unclear." (PMID 40948742, 2025). "In pulmonary arterial hypertension (PAH)-induced right ventricular failure, there was a significant increase in the number of macrophages within the right ventricle, accompanied by an elevated expression of the NLRP3 inflammasome in these macrophages." (PMID 39925805, 2025). "Interestingly, mice lacking NLRP3 display attenuated pulmonary hypertension and a blunted inflammasome activation with decreased caspase-1, IL-18, and IL-1β levels in response to hypoxia induced pulmonary vasoconstriction." (PMID 31915037, 2020).
head and neck squamous cell carcinoma (28 papers, 2017 to 2025). A squamous cell carcinoma that arises from any of the following anatomic sites: lip and oral cavity, nasal cavity, paranasal sinuses, pharynx, larynx, and salivary glands. "In the head and neck squamous cell carcinoma, treatment with the NLRP3 inhibitor MCC950 decreased sphere and colony formation as well as cancer stem cell marker BMI1, ALDH1, and CD44 expression." (PMID 38904007, 2024). "NLRP3 expression was detected in high levels in many types of tumors, such as head and neck squamous cell carcinoma, laryngeal squamous cell carcinoma, bladder cancer, and prostate cancer, compared to their nontumor tissue samples." (PMID 36902278, 2023). "This is supported by studies showing that activation of NLRP3 inflammasome/IL-1β pathway promotes head and neck squamous cell carcinoma tumorigenesis while inactivation of this pathway delayed tumor growth." (PMID 34357109, 2021). "It was reported that the inhibition of NLRP3 inflammasome by MCC950 delayed the progression of tumor growth in mice with head and neck squamous cell carcinoma." (PMID 34211462, 2021). "Huang et al80 documented that activation of NLRP3 inflammasome contributes to carcinogenesis in head and neck squamous cell carcinoma via promoting chronic inflammation or angiogenesis." (PMID 34590363, 2021). "There is increasing evidence that the expression of the NLRP3 inflammasome is dysregulated in many cancers, such as head and neck squamous cell carcinoma, hepatocellular carcinoma, and colorectal cancer." (PMID 31632911, 2019). "For instance, the NLRP3 inflammasome/IL-1β pathway enhanced immunosuppressive cell accumulation to facilitate the tumorigenesis of head and neck squamous cell carcinoma (HNSCC)." (PMID 31492049, 2019). "NLRP3 inflammasome can be a potential target in the development of novel approaches for head and neck squamous cell carcinoma therapy." (PMID 28865486, 2017). "Available studies previously reported that several scorch death‐related genes, including NLRP1 and NLRP3, play a key role in cancer immunity and may be employed as prognostic factors in pancreatic, breast, lung, and head and neck squamous cell carcinomas." (PMID 39318060, 2024). "This includes MCC950, a diarylsulfonylurea-containing compound that inhibits ATP hydrolysis in the NACHT domain of NLRP3, which has been found to suppress MDSCs and regulatory T cells while enhancing the numbers of effector T cells in murine models of head and neck squamous cell carcinoma." (PMID 34638239, 2021). "NLRP3 inflammasome activation has been demonstrated to promote inflammation-induced carcinogenesis in head and neck squamous cell carcinoma (HNSCC), and P2 × 7R and NLRP3 have been found to be overexpressed in HNSCC in association with increased survival and invasiveness." (PMID 34064909, 2021). "Finally, the NLRP3 inflammasome has a key role in promoting progression and invasion of head and neck squamous cell carcinoma, as evidenced by studies showing that NLRP3 inflammasome components are over-expressed in squamous cell carcinoma tissues." (PMID 33014808, 2020). "Furthermore, the overactivation of NLRP3 was related to poor survival and tumor invasiveness in head and neck squamous cell carcinoma and breast cancer." (PMID 31632911, 2019). "Therefore, it is concluded that the purinergic receptor P2X7 and the activation of NLRP3 inflammasome play important roles in the survival and invasiveness of head and neck squamous cell carcinoma in humans." (PMID 28430665, 2017). "NLRP3-mediated inflammation drives carcinogenesis in head and neck squamous cell carcinoma (HNSCC), where NLRP3 protein, whose level correlates with cancer invasiveness, has been found overexpressed." (PMID 37891577, 2023). "In head and neck squamous cell carcinoma (HNSCC), overexpression and constitutive activation of the NLRP3 inflammasome was closely correlated with carcinogenesis and enhanced self-renewal capacity of cancer stem cells." (PMID 33918087, 2021).